CDK8 (cyclin dependent kinase 8)
Diseases named in the same sentence as CDK8 in open-access papers (continued):
Sharing a sentence is not in itself a finding about the gene and the disease.
cutaneous melanoma (3 papers, 2020 to 2021). A primary melanoma arising from atypical melanocytes in the skin. "The tumor suppression function of macroH2A1 in cutaneous melanoma was attributed to a large extent to the transcriptional suppression of CDK8, a known oncogene." (PMID 32401230, 2020). "MacroH2A1 and CDK8 expression levels anti-correlate in human cutaneous melanoma patient samples." (PMID 32401230, 2020). "The specific role of CDK8 in UM progression has not been investigated so far, although pan-CDK inhibition seems to be partially effective both in cutaneous melanoma and in UM." (PMID 32401230, 2020).
endometrial cancer (3 papers, 2021 to 2024). Primary or metastatic malignant neoplasm involving the endometrium (mucous membrane that lines the endometrial cavity). "CDK8 deficiency increases lipid gene expression in endometrial cancer cells." (PMID 36072980, 2022). "Cyclin-dependent kinase 8 (CDK8) is a member of the transcriptionally regulated CDK family, and in an in vivo mouse model, ectopic expression of CDK8 in KLE cells in endometrial cancer inhibits cell proliferation and effectively blocks tumor growth." (PMID 36072980, 2022). "However, CDK8 exerts an anticancer role in endometrial cancer in addition to its role in tumor growth, implying that CDK8 has a different function in the growth of cancer." (PMID 38606172, 2024). "The tumor suppressor effect of CDK8 was also observed in endometrial cancer." (PMID 33686962, 2021).
lymphoma (3 papers, 2015 to 2022). A malignant (clonal) proliferation of B- lymphocytes or T- lymphocytes which involves the lymph nodes, bone marrow and/or extranodal sites. "Recent evidence from the inhibition of Cdk8 kinase activity in lymphoma cells suggests a repressive function for Cdk8 on genes that are regulated by super-enhancers." (PMID 32439758, 2020).
non-small cell lung carcinoma (3 papers, 2021 to 2024). A group of at least three distinct histological types of lung cancer, including non-small cell squamous cell carcinoma, adenocarcinoma, and large cell carcinoma. "In non-small cell lung cancer, CDK8/FBXW7-mediated NICD1 degradation can be competitively abolished by RFC4 (a DNA replication factor), which results in increased NICD1 stability and promotes NSCLC invasiveness." (PMID 38606172, 2024). "Overexpression of CDK8 in Non-small cell carcinoma (NSCLC) partially reverses miR-138-5p-induced G0/G1 phase arrest in NSCLC, thereby promoting the growth of non-small cell carcinoma." (PMID 38606172, 2024).
osteoporosis (3 papers, 2022 to 2026). A condition of reduced bone mass, with decreased cortical thickness and a decrease in the number and size of the trabeculae of cancellous bone (but normal chemical composition), resulting in increased fracture incidence. "Prior literature has demonstrated that Cdk8 is upregulated under aging-associated osteoporosis and that genetic inhibition of Cdk8 rescued the impaired senescent MSC phenotype in aged mice." (PMID 40470203, 2025). "In addition to tumor growth inhibition, CDK8 inhibitors have also been shown to suppress osteoclast function, suggesting their potential as prophylactic and therapeutic agents for osteoporosis." (PMID 41493967, 2026). "Moreover, they showed that pharmacological inhibition of CDK8 represses MSC-dependent osteoclastogenesis and prevents ovariectomy-induced osteoclastic activation and bone loss, highlighting a potential target against osteoporosis with abnormal osteoclastogenesis." (PMID 35777359, 2022).
ovarian carcinoma (3 papers, 2023 to 2026). A malignant neoplasm originating from the surface ovarian epithelium. "Both anoikis resistance and in vivo metastatic growth of ovarian cancers are sensitive to CDK8/19 inhibition, thereby providing a therapeutic opportunity to both prevent and suppress ovarian cancer metastasis." (PMID 41538289, 2026). "Critically, selective inhibitors of CDK8/19 Mediator kinase, a pleiotropic regulator of transcriptional reprogramming, prevent anoikis adaptation and metastasis in ovarian cancer models." (PMID 38106208, 2023). "This dependency on Mediator kinase presents a new therapeutic opportunity for the use of CDK8/19 inhibitors for the management of ovarian cancer in the clinic." (PMID 38106208, 2023). "The present study reveals that targeting CDK8/19i can provide a strategy for potentiating the cytotoxic effects of existing chemotherapeutics used in OCCC treatment and proposes potent CDK8/19is as a viable option for further exploration and optimization in the treatment of ovarian cancers." (PMID 40149277, 2025). "CDK8 has been outlined as a proto-oncogene, with multiple studies correlating elevated CDK8 expression to poor clinical prognosis in various solid malignant tumors, including ovarian cancer." (PMID 40149277, 2025).
viral infection (3 papers, 2018 to 2023). "Next, we addressed the role of CDK8/19 in monocyte functional manifestation during viral infection or LPS exposure." (PMID 37376593, 2023). "As such, therapeutics that target CDK8/19 enzyme activity offer promise for virus infection as well as cancer." (PMID 32560467, 2020). "Though we used HK2 and LC3 as measures of CDK8/19-dependent metabolic gene expression during DENV2 infection, these are likely not the only genes regulated by CDK8/19 during viral infection." (PMID 32560467, 2020).
cervical carcinoma (2 papers, 2019 to 2023). A carcinoma arising from either the exocervical squamous epithelium or the endocervical glandular epithelium. "Analysis of survival correlations identified a group of cancers where CDK8 expression correlated with shorter survival (notably breast, prostate, cervical cancers, and esophageal adenocarcinoma)." (PMID 31382571, 2019).
colorectal adenoma (2 papers, 2019 to 2020). An adenoma that arises from the colon or rectum. "An increased level of CDK8 was later found in advanced CRC stages III and IV, suggesting that CDK8 contributes to the progression of colorectal adenoma to carcinoma." (PMID 31248103, 2019). "In addition, increased level of CDK8 was later found in advanced CRC stages III and IV, suggesting that CDK8 contributes to the progression of colorectal adenoma to carcinoma." (PMID 32596239, 2020).
experimental autoimmune encephalomyelitis (2 papers, 2019 to 2024). An autoimmune demyelinating disease of the central nervous system that is produced experimentally in animals by the injection of homogenized brain or spinal cord in Freund's adjuvant. "Importantly, treatment with Cdk8/Cdk19 inhibitor CCT251921 significantly increased Treg population and ameliorated autoimmune symptoms in an experimental autoimmune encephalomyelitis (EAE) model." (PMID 31552016, 2019).
gastric adenocarcinoma (2 papers, 2015 to 2019). "Remarkably, some cancers, in particular stomach adenocarcinoma and esophageal squamous cell carcinoma, showed the opposite correlations for CDK8 expression, as it was associated with longer patient survival, suggesting that the Mediator kinase may play a tumor-suppressive role in such cancers." (PMID 31382571, 2019). "Likewise, CDK8 was found to be overexpressed in gastric adenocarcinomas and CDK8 expression and the delocalization of β-catenin expression showed a significant positive correlation with carcinogenesis and tumor progression." (PMID 25625291, 2015).
lung fibrosis (2 papers, 2024 to 2025). "We discovered that CDK8 is upregulated in lung tissues from idiopathic pulmonary fibrosis patients and in a bleomycin-induced PF mouse model." (PMID 39781457, 2025). "Overall, this study revealed E966-0530-45418, a CDK8 inhibitor, for the first time to target CDK8 in an attempt to treat pulmonary fibrosis." (PMID 39781457, 2025). "In the present study, we revealed a novel mechanism by which circMKLN1 acts as a miR-26a/b sponge to promote CDK8 expression in the EMT process of pulmonary fibrosis." (PMID 38460002, 2024). "The increase in CDK8 expression may be related to the regulation of miRNA-770, as previous studies have shown an inverse correlation between miRNA-770 expression and CDK8 expression 42, and miRNA-770 is inhibited by TGFβ1 in lung fibrosis." (PMID 39781457, 2025). "Notably, analysis of the GSE191279 dataset indicated that prolonged exposure of alveolar epithelial cells (AECs) to TGFβ (6 days) resulted in elevated CDK8 mRNA expression, which may provide a mechanistic explanation for the increased CDK8 expression observed in lung fibrosis." (PMID 39781457, 2025). "Our research indicated that circMKLN1 promoted CDK8 expression through sponge adsorption of miR-26a/b, which regulates EMT and pulmonary fibrosis." (PMID 38460002, 2024).
medulloblastoma (2 papers, 2016 to 2024). A malignant, invasive embryonal neoplasm arising from the cerebellum. "Importantly, MYC-driven medulloblastoma exhibited the most significant susceptibility to the loss of CDK8 among all cancer types." (PMID 39574899, 2024). "CDK8 is critical for various types of cancer, with MYC-driven medulloblastoma being the most sensitive cancer type to the loss of CDK8." (PMID 39574899, 2024). "In conclusion, our data suggest that the CDK8 inhibitor RVU120 is a promising agent for MYC-driven medulloblastoma therapy and provides a mechanistic basis for future research." (PMID 39574899, 2024). "Here, we identified MYC-driven medulloblastoma as one of the most significantly affected cancer types following CDK8 depletion, demonstrating the essential role of CDK8 in driving medulloblastoma growth." (PMID 39574899, 2024). "CDK8 stands out as a top dependency, similar to OTX2, Neurog1, and Neurod1, well-established genes that sustain stemness and drive proliferation in medulloblastoma 34–37." (PMID 39574899, 2024). "This work holds the promise of significantly advancing our understanding of MYC-driven oncogenesis and provides critical preclinical data essential for the development of novel therapies targeting CDK8 and mTOR in MYC-driven medulloblastoma." (PMID 39574899, 2024).
Obesity (2 papers, 2015 to 2023). Accumulation of substantial excess body fat. "In mouse models of obesity and aging, hepatic mTORC1 is activated and the CDK8-CycC complex is decreased, correlated with the accumulation of nuclear SREBP-1c proteins and lipogenic enzymes." (PMID 26042770, 2015). "To examine the potential role of the CDK8-CycC complex in obesity, insulin resistance and NAFLD, we first examined the protein expression profiles in both leptin receptor-deficient (db/db) and leptin-deficient (ob/ob) mice, two well-studied models of obesity with insulin resistance and fatty liver." (PMID 26042770, 2015). "Both mouse models of obesity displayed significantly lower levels of CDK8 and CycC proteins." (PMID 26042770, 2015). "Recently, remarkably decreased protein amounts of cyclin-dependent kinase 8 (CDK8) and Cyclin C (CycC) were detected in obesity in comparison with normal livers." (PMID 36769165, 2023).
rectal cancer (2 papers, 2017 to 2024). A primary or metastatic malignant neoplasm that affects the rectum. "Next, we tested the combination of ERK and CDK8/19 inhibition in three KRAS-mutant, patient-derived tumoroid models of rectal cancer." (PMID 38822082, 2024).
renal carcinoma (2 papers, 2019 to 2025). A carcinoma arising from the epithelium of the renal parenchyma or the renal pelvis. "Among the most critical signaling cascades in RCC are the Wnt/β-catenin pathway and the CDK8-mediated transcriptional regulation pathway, both of which play pivotal roles in driving renal cancer cell proliferation and metastasis." (PMID 40699862, 2025). "This study aims to identify novel dual inhibitors of tankyrase and Cyclin-dependent kinase 8 (CDK8), utilizing bioinformatics and in vitro methods and to assess their efficiency in renal cancer cells." (PMID 40699862, 2025). "Focusing on the RCC, a combination of methylome and transcriptome analyses confirmed the mediators of the CDK8 complex to directly regulate the β-catenin-driven transcription of the Wnt/β-catenin signaling pathway in renal cancer samples." (PMID 40699862, 2025). "These signaling pathways are known to play crucial roles in renal cancer cell proliferation and metastasis, making TNKS1 and CDK8 promising therapeutic targets for cancer treatment." (PMID 40699862, 2025). "By targeting both TNKS1 and CDK8, TCS9725 is expected to disrupt critical signaling pathways involved in renal cancer progression, including STAT1, β-Catenin, and TGFβ1-Smad signaling, which are known to drive cancer cell proliferation and metastasis." (PMID 40699862, 2025).
age-related macular degeneration (1 paper, 2025). Age-related loss of vision in the central portion of the retina (macula), secondary to retinal degeneration. "CDK8 can promote Vascular Endothelial Growth Factor (VEGF) expression via the β-catenin-KLF2 axis, thereby driving angiogenesis, which is implicated in retinal diseases such as diabetic retinopathy (DR) and age-related macular degeneration (AMD) through increased VEGF signaling." (PMID 41427248, 2025).
aortic valve disease (1 paper, 2026). "PDE3A and CDK8 have all been previously linked to cardiovascular disease or physiology, although not specifically to aortic valve disease, whereas the link between MN1 and cardiovascular disease remains largely unexplored." (PMID 41419685, 2026).
autoimmune disease (1 paper, 2019). A disorder resulting from loss of function or tissue destruction of an organ or multiple organs, arising from humoral or cellular immune responses of the individual to their own tissue constituents. "In addition, investigating the role of Cdk8/Cdk19 inhibition on other autoimmune diseases such as graft-vs.-host disease, SLE, and rheumatoid arthritis (RA) will further confirm the function of Cdk8/Cdk19 in adaptive immunity regulation and diversify its application in the field of autoimmunity." (PMID 31552016, 2019).
Autoimmunity (1 paper, 2019). The occurrence of an immune reaction against the organism's own cells or tissues. "In the present study, we demonstrated that Cdk8 inhibition promoted Treg cell differentiation and suppressed autoimmunity in the EAE model." (PMID 31552016, 2019). "To investigate whether Cdk8/Cdk19 inhibition promoted Treg cells were functionally competent to suppress autoimmunity in vivo, we analyzed the inhibitory effect of CCT251921 in EAE model." (PMID 31552016, 2019).
bone cancer (1 paper, 2023). A primary or metastatic malignant neoplasm affecting the bone or articular cartilage. "As expected, miR-PC-2869 regulates the expression of CDK8, EEF1A1, and NTN1 in both human bone cancer and deer antler cells, suggesting that conserved target sites underlie the cross-species regulation of miR-PC-2869." (PMID 37446017, 2023). "Notably, cyclin-dependent kinase 8 (CDK8), eukaryotic translation elongation factor 1 alpha 1 (EEF1A1), and netrin 1 (NTN1), three functional targets of miR-PC-2869, jointly mediate the cellular functions of miR-PC-2869 in antler growth and bone cancers." (PMID 37446017, 2023).
chondrosarcoma (1 paper, 2023). A malignant cartilaginous matrix-producing mesenchymal neoplasm arising from the bone and soft tissue. "To assess whether miR-PC-2869 exerts inhibitory effects on chondrosarcoma cells by downregulating CDK8, EEF1A1, and NTN1, we employed RNA interference to individually knock down the expression of each gene in SW1353 cells." (PMID 37446017, 2023).
chronic leukemia (1 paper, 2023). A slowly progressing leukemia characterized by a clonal (malignant) proliferation of maturing and mature myeloid cells or mature lymphocytes. "mNK cells isolated from CDK8-deficient Cdk8fl/flNcr1Cre mice exhibited increased cytotoxicity against YAC-1 cells in vitro, while Cdk8fl/flNcr1Cre mice had longer survival in a chronic leukemia model compared with control." (PMID 37377891, 2023).
colitis (1 paper, 2023). Inflammation of the colon. "To further investigate roles of CDK8 in intestinal tumourigenesis, we used a colitis‐associated chemical model of intestinal tumourigenesis (azoxymethane‐dextran sodium sulphate, AOM‐DSS), combined with acute deletion of Cdk8." (PMID 36545778, 2023).
colorectal adenocarcinoma (1 paper, 2019). The most common type of colorectal carcinoma. "Pharmacological screening for potent Cdk8 inhibitors is of utmost importance since, in line with its oncogenic role, Cdk8 has been identified as the down-stream effector of the Wnt/β-catenin pathway in colorectal adenocarcinoma." (PMID 30621145, 2019).
colorectal tumors (1 paper, 2016). "CDK8 activity maintains embryonic stem cells in an undifferentiated, pluripotent state and colorectal tumors in a de-differentiated state." (PMID 27935476, 2016). "Treating these mice with prototype CDK8/19 drugs inhibited the activity of CDK8 and CDK19 in the cancer cells and slowed the growth of colorectal tumors." (PMID 27935476, 2016).
cystic fibrosis (1 paper, 2023). Autosomal recessive disorder caused by pathogenic variants in the CFTR gene (cystic fibrosis transmembrane conductance regulator), which encodes a chloride and bicarbonate channel expressed in epithelial cells, and follow the diagnosis criteria. "We uncover an unexpected requirement for these kinases in control of the CFTR pathway, a key player in cystic fibrosis, and show that CDK8/19 inhibition can modulate mucus production in organoids and in vivo." (PMID 36545778, 2023). "Whether or not CDK8 or CDK19 are implicated in the pathogenesis of cystic fibrosis also remains an open question." (PMID 36545778, 2023). "Identifying the mechanisms by which CDK8 and CDK19 affect expression of genes in the CFTR pathway may improve understanding the pathophysiology of cystic fibrosis, but will require further studies." (PMID 36545778, 2023).
ductal breast carcinoma (1 paper, 2021). "In turn, CDK8 mRNA expression was increased in ductal breast carcinoma (fold change = 1.670) in Richardson’s dataset." (PMID 33686962, 2021).
esophageal squamous cell carcinoma (1 paper, 2019). Esophageal squamous cell carcinoma (ESCC) is a type of esophageal carcinoma (EC) that can affect any part of the esophagus, but is usually located in the upper or middle third. "In contrast, CDK8 expression was correlated with longer OS in esophageal squamous cell carcinoma." (PMID 31382571, 2019).
gynecological cancers (1 paper, 2025). "In this study, we explored the effect of CDK8/19 inhibition on OC tumor growth, disease progression, and chemotherapeutic response, showing for the first time that the use of a CDK8/19i, especially in combination with platinum-based therapy, is clinically translatable for gynecological cancers." (PMID 40149277, 2025).
heart failure (1 paper, 2024). Inability of the heart to pump blood at an adequate rate to meet tissue metabolic requirements. "High-dose EPO also increased heart failure-associated genes such as Cdk8, Nox4, S100A, and SERCA2a, and hypertrophic cardiomyopathy-related genes such as Acta1, Myh7, Nppa, and Nppb in male WT mice but not in ΔEPORE male mice." (PMID 38628440, 2024). "ΔEPORE mice showed increased expression of two-fold or more of heart failure-associated genes Cdk8, TGFb2, Nox4, S100A, and SERCA2a." (PMID 38628440, 2024). "In nNOS−/− mice, the expression levels of heart failure-associated genes Cdk8, TGFβ2, and NOX4 and hypertrophic cardiomyopathy-related gene Nppa were analogous to levels in WT mice." (PMID 38628440, 2024). "Among the genes examined were Cdk8, for which increased transgenic expression in mice promotes heart failure, TGFβ that exhibits elevated levels in myocardial infarction, and Nox4 that is a major source of reactive oxygen species." (PMID 38628440, 2024). "However, while EPO treatment increased expression of these heart failure-associated genes in WT mice, EPO treatment did not change expression of heart failure-associated genes Cdk8, TGFβ2, and NOX4 and hypertrophic cardiomyopathy-related genes Nppa in nNOS−/− mice." (PMID 38628440, 2024).